SUN2 (Sad1 and UNC84 domain containing 2)
Description:
As a component of the LINC (LInker of Nucleoskeleton and Cytoskeleton) complex, involved in the connection between the nuclear lamina and the cytoskeleton. The nucleocytoplasmic interactions established by the LINC complex play an important role in the transmission of mechanical forces across the nuclear envelope and in nuclear movement and positioning. Specifically, SYNE2 and SUN2 assemble in arrays of transmembrane actin-associated nuclear (TAN) lines which are bound to F-actin cables and couple the nucleus to retrograde actin flow during actin-dependent nuclear movement. Required for interkinetic nuclear migration (INM) and essential for nucleokinesis and centrosome-nucleus coupling during radial neuronal migration in the cerebral cortex and during glial migration. Required for nuclear migration in retinal photoreceptor progenitors implicating association with cytoplasmic dynein-dynactin and kinesin motor complexes, and probably B-type lamins; SUN1 and SUN2 seem to act redundantly. The SUN1/2:KASH5 LINC complex couples telomeres to microtubules during meiosis; SUN1 and SUN2 seem to act at least partial redundantly. Anchors chromosome movement in the prophase of meiosis and is involved in selective gene expression of coding and non-coding RNAs needed for gametogenesis. Required for telomere attachment to nuclear envelope and gametogenesis. May also function on endocytic vesicles as a receptor for RAB5-GDP and participate in the activation of RAB5.
Synonyms: Rab5IP; UNC84B
Tractability: Small molecule: a structure with a bound ligand is known. Antibody: UniProt places it where antibodies can reach, with high confidence; UniProt predicts a signal peptide or a membrane-spanning region. PROTAC: ubiquitination databases record sites on it; its protein half-life has been measured.
Gene: Protein-coding gene on chromosome 22 (38,733,280 to 38,794,143, reverse strand). Ensembl gene ENSG00000100242.
Subcellular location: Nucleus inner membrane; Nucleus envelope; Endosome membrane
Subcellular location (Human Protein Atlas): Nuclear membrane
Pathways (Reactome):
Disease: Dengue Virus Genome Translation and Replication
Reproduction: Meiotic synapsis
Gene Ontology:
Molecular function: cytoskeleton-nuclear membrane anchor activity; identical protein binding; lamin binding; protein binding; microtubule binding
Biological process: nuclear matrix anchoring at nuclear membrane; centrosome localization; mitotic spindle organization; nuclear migration; nuclear migration along microfilament; positive regulation of cell migration; nucleokinesis involved in cell motility in cerebral cortex radial glia guided migration
Cellular component: endosome membrane; meiotic nuclear membrane microtubule tethering complex; nuclear envelope; nuclear inner membrane; nuclear membrane; chromosome, telomeric region; condensed nuclear chromosome
Genetic constraint (gnomAD): Loss-of-function variants: 60 observed, 98.44 expected, observed/expected ratio (o/e) 0.61, 90% interval 0.49 to 0.76. The upper end of that interval is the gene's LOEUF score, 0.76, which puts it in group 3 of 6, group 1 being the genes least tolerant of losing a copy. Missense variants: 834 observed, 973.41 expected, observed/expected ratio (o/e) 0.86, 90% interval 0.81 to 0.91. Synonymous variants: 367 observed, 413.31 expected, observed/expected ratio (o/e) 0.89, 90% interval 0.81 to 0.97.
Homologues: Orthologues: chimpanzee SUN2 (99% identical), macaque SUN2 (97% identical), dog SUN2 (86% identical), pig SUN2 (85% identical), mouse Sun2 (83% identical), guinea pig SUN2 (82% identical), rat Sun2 (82% identical), rabbit SUN2 (57% identical), tropical clawed frog sun2 (44% identical), zebrafish sun2 (32% identical). Paralogues in human: SUN1 (31% identical), SUN3 (17% identical), SPAG4 (16% identical), SUN5 (14% identical).
Diseases named in the same sentence as SUN2 in open-access papers:
SUN2 is named in the same sentence as 62 diseases in open-access papers, as found by Europe PMC text mining. Sharing a sentence is not in itself a finding about the gene and the disease. The quoted sentences say what the papers report.
breast carcinoma (12 papers, 2015 to 2026). "Collectively, these results demonstrated that breast cancer cells respond to changes in cytosolic Ca2+ concentrations by modulating the expression of lamin A/C and SUN2, thereby sensing and responding to mechanical signals." (PMID 41356797, 2026). "Knockdown of SUN2 in invasive breast cancer cells impaired the splicing of sororin, which stabilizes sister chromatids during DNA replication." (PMID 39866838, 2025). "While PDIs tend to be overexpressed in cases of advanced breast cancer, the LINC complex proteins Nesprin-2, SUN1, SUN2, and Lamin A/C are downregulated in human breast cancer cells." (PMID 38891038, 2024). "The role of SUN2 as cancer suppressor was demonstrated in various cancers, including embryonal tumors, breast cancer, lung cancer, and PCa." (PMID 35372566, 2022). "Analysis of The Cancer Genome Atlas (TCGA) dataset further confirmed that the expression of SUN1 and SUN2 is downregulated in breast cancer compared to normal breast tissue." (PMID 34205257, 2021). "The role of Sun2 has been described by previous studies in various types of cancers, including breast cancer and lung cancer." (PMID 29163775, 2017). "In this study we performed immunohistochemistry to demonstrate reduced expression of four LINC complex and nuclear lamina components, SUN1, SUN2, nesprin-2, and lamin A/C, in breast cancer tissues." (PMID 26175118, 2015). "Using immunohistology, we found that a nuclear lamina component, lamin A/C and all of the investigated LINC complex components, SUN1, SUN2, and nesprin-2, were downregulated in human breast cancer tissues." (PMID 26175118, 2015). "It has been emphasized that decreased expression of the SUN2 gene in breast cancer tissues may be critical for cancer prognosis." (PMID 38627780, 2024). "Abnormal regulation of LINC complex genes SUN1, SUN2 and nesprin 2 is also seen in breast cancer." (PMID 32942630, 2020). "Hence, in this study we examined the protein expression levels of a nuclear lamina component, lamin A/C, and three LINC complex components, SUN1, SUN2, and nesprin-2 in breast cancer tissue." (PMID 26175118, 2015). "Sun2 expression was also decreased in breast cancer and may play a tumor suppressor role." (PMID 29163775, 2017). "Applied to human breast cancer cells, LIV decreased matrix invasion and impaired secretion of osteolytic factors in a SUN1‐ and SUN2‐dependent manner." (PMID 39866838, 2025). "One of the first interactions that emerged in breast cancer tissue compared to normal tissue was the interaction between RMND5A, EIF5B, SUN2, KLHL18, KDSR, RPSK6KA3 ceRNAs and the miR-338-5p, miR-223-3p, miR-129-5p, miR-642a-5p, miR-3619-5p, and miR-382-5p miRNAs." (PMID 38627780, 2024). "We demonstrated significantly reduced expression of SUN1, SUN2, and nesprin-2 proteins in breast cancer (SUN1, 88%; SUN2, 74%; nesprin-2, 79%) regardless of clinicopathological classification and all patients exhibited reduced expression of at least one of four components." (PMID 26175118, 2015). "Moreover, the data indicate oligomerisation differences in SUN2 and Lamin B1, between non-invasive mammary epithelium (MCF10A) and invasive cancer (MDA-MB-231) cells in vitro, suggesting a mechanism by which the LINC complex influences breast cancer cell behaviour." (PMID 38891038, 2024). "Furthermore, several cultured breast cancer cell lines expressed less SUN1, SUN2, nesprin-2 mRNA, and lamin A/C compared to noncancerous mammary gland cells." (PMID 26175118, 2015).
HIV-1 infection (7 papers, 2017 to 2023). The type species of lentivirus and the etiologic agent of acquired immunodeficiency syndrome (AIDS). "SUN2 (Sad1 and UNC84 domain containing 2) is associated with mitosis, maintains a repressive chromatin state, and inhibits HIV-1 infection via association with Lamin A/C." (PMID 37936693, 2023). "Taken together, these data proved that the reactivation and replication of HIV-1 disassociate the SUN2-lamin A/C complex, demonstrating the reversibility of the association of SUN2 with lamin A/C during HIV-1 infection." (PMID 29717016, 2018). "The depletion of SUN1 had no observable effect on infection by either virus, whereas the loss of SUN2 resulted in an ∼2- to 3-fold reduction in HIV-1 infection compared to a CRISPR/Cas9 control cell clone expressing an irrelevant control gRNA." (PMID 28747499, 2017). "Taken together, these observations suggest that SUN1 and SUN2 may function redundantly to modulate postentry, nuclear-associated steps of HIV-1 infection." (PMID 28747499, 2017). "Overexpression of the human protein SUN2 was originally discovered to affect HIV-1 infection in a screen that tested the ability of interferon-stimulated genes to block HIV-1 infection." (PMID 34580332, 2021). "Overexpression of the human Sad-1-Unc-84 homology protein 2 (SUN2) blocks HIV-1 infection in a capsid-dependent manner." (PMID 34580332, 2021). "Overexpression of SUN1 or SUN2 blocks HIV-1 infection; however, the role of endogenously expressed SUN1 and SUN2 in HIV-1 replication is not clear." (PMID 34580332, 2021). "Although overexpression of SUN2 blocks HIV-1 infection, we observed that this block is less potent when compared to SUN1." (PMID 34580332, 2021). "Overall these experiments suggested that SUN2 residues 30–60 are required for its ability to block HIV-1 infection." (PMID 34580332, 2021). "To understand weather the subcellular localization of SUN1 and SUN2 are important for their ability to block HIV-1 infection, we analyzed subcellular localization of the different SUN1 and SUN2 variants." (PMID 34580332, 2021). "To explore the role of capsid in the ability of SUN1 and SUN2 (SUN1/2) to block HIV-1 infection, we measured the ability of SUN1/2 to bind to the HIV-1 core." (PMID 34580332, 2021). "Our previous experiments suggested that the N-terminal domain of SUN2 is required for its ability to block HIV-1 infection, which is in agreement with the fact that the N-terminus of SUN2 is localized to the nucleoplasm." (PMID 34580332, 2021). "This coincides with the fact that the overexpression of SUN2 inhibits HIV-1 infection in primary monocyte-derived cells." (PMID 32854281, 2020). "To prepare for detailed mechanistic studies, we performed a similar assessment of the inhibitory role of SUN2 on HIV-1 infection in the Jurkat CD4+ T-cell line." (PMID 29717016, 2018). "In this study, we provide novel insights into the mechanisms by which the endogenous SUN2 mediates the inhibition of HIV-1 infection." (PMID 29717016, 2018). "Our finding provides novel insights into SUN2-mediated modulation of HIV-1 infection and facilitates a better understanding of host modulation of HIV-1 latency." (PMID 29717016, 2018). "The overexpression of SUN2 has previously been reported to inhibit HIV-1 infection in cell lines and primary monocyte-derived dendritic cells (MDDCs)." (PMID 29717016, 2018). "Taken together, these data demonstrate that SUN2 inhibits HIV-1 infection by suppressing the transcription of proviral DNA." (PMID 29717016, 2018). "Several recent studies published in quick succession have suggested that manipulation of SUN2 can either inhibit or promote HIV-1 infection, depending on the level of expression." (PMID 29056936, 2017). "In summary, endogenous SUN2 appears to play a central role in T cell proliferation and activation, which indirectly makes it essential for HIV-1 infection of activated primary T cells in culture." (PMID 29056936, 2017).
HIV-1 infection (continued). "Our data suggested that the viral determinant for SUN1- as well as SUN2-mediated inhibition of HIV-1 infection is located in the HIV-1 CA protein; for example, HIV-1 harboring the CA from SIVmac was largely insensitive to SUN1 (data not shown)." (PMID 28747499, 2017). "We addressed the contributions of the endogenous SUN1 and SUN2 proteins to HIV-1 infection in the myeloid cell line THP-1 by generating single-cell clones in which SUN1 or SUN2 had been knocked out." (PMID 28747499, 2017). "During the preparation of the manuscript, three further studies were published reporting a possible role for SUN2 in early HIV-1 infection steps." (PMID 28747499, 2017). "We found that the integral transmembrane proteins SUN1/UNC84A and SUN2/UNC84B are potent or modest inhibitors of HIV-1 infection, respectively, and that suppression corresponds to defects in the accumulation of viral cDNA in the nucleus." (PMID 28747499, 2017). "Several groups have confirmed that SUN2 overexpression leads to a block to HIV-1 infection and replication, as originally reported in Ref." (PMID 29056936, 2017). "An overexpression screen identified the inner nuclear membrane proteins SUN1 and SUN2 as potential effectors of HIV-1 infection." (PMID 28747499, 2017). "SUN2 had previously emerged from a functional cDNA screen as a type I interferon (IFN)-induced gene that blocks HIV-1 infection." (PMID 28747499, 2017). "In the same manner as SUN1, we tested the hypothesis that the N-terminal domain of SUN2 is interacting with the HIV-1 replication complex in the nucleus consequentially affecting HIV-1 infection." (PMID 34580332, 2021). "Next we tested the ability of SUN2 to block HIV-1 infection." (PMID 34580332, 2021). "These experiments are in agreement with our hypothesis that the N-terminal domain is important for the ability of SUN2 to bind capsid and restrict HIV-1 infection." (PMID 34580332, 2021). "Results showed that SUN2 knockdown significantly increased HIV-1 infection." (PMID 29717016, 2018). "We found that the stimulation of resting CD4+ T cells with either PHA-P or the anti-CD3/CD28 antibodies could significantly diminish SUN2 expression, which helps to explain the increased susceptibility of activated primary CD4+ T cells for HIV-1 infection." (PMID 29717016, 2018). "We speculate that SUN1/SUN2 may function redundantly in early HIV-1 infection steps and therefore influence HIV-1 replication and pathogenesis." (PMID 28747499, 2017). "We next sought to address the role of endogenous SUN1 or SUN2 proteins in HIV-1 infection." (PMID 28747499, 2017). "It is possible that SUN1 and SUN2 provide redundant functions for HIV-1 infection; however, simultaneous depletion of both proteins can result in mitotic defects and delayed cell proliferation, thus confounding the interpretation of virus infection experiments." (PMID 28747499, 2017). "Second, shRNA-mediated depletion of SUN2 in human primary CD4+ T cells decreased permissivity to HIV-1 infection and the inhibition of CypA function only had a minor effect in SUN2-depleted cells, while in control cells CypA inhibition caused a significantly greater reduction in HIV-1 infection." (PMID 28747499, 2017). "We found that ectopic expression of UNC-84A/SUN1 or UNC-84B/SUN2 inhibits HIV-1 infection." (PMID 28747499, 2017). "Overexpression of the INM protein Sad1/UNC-84 domain-containing 2 (SUN2) has recently been described to inhibit HIV-1 infection, and we asked whether other proteins exert a similar activity." (PMID 28747499, 2017). "However, depletion of SUN2 using CRIPSR/Cas9 in THP-1 cells mildly affected HIV-1 infection." (PMID 34580332, 2021). "These experiments suggested that expression of SUN1 and/or SUN2 is not important for HIV-1 infection of HAP-1 cells." (PMID 34580332, 2021).
HIV-1 infection (continued). "We found that HAP1 SUN1, SUN2, or SUN1/SUN2 knockout cells were permissive to HIV-1 infection, suggesting that this system is not providing evidence for a functional contribution of SUN1 or SUN2 to HIV-1 infection." (PMID 34580332, 2021). "For this purpose, we generated knockouts for the expression of SUN1 and/or SUN2 in human haploid HAP-1 cells, and investigated whether HIV-1 infection is affected." (PMID 34580332, 2021). "The results suggest that the CypA effects on HIV-1 infection are not changed by SUN1 or SUN2 gene knockout." (PMID 28747499, 2017). "In conclusion, we propose that the amino-terminal domains of SUN1 and SUN2 may interact with incoming HIV-1 subviral CA-containing replication complexes and facilitate steps during early HIV-1 infection, possibly in a redundant fashion." (PMID 28747499, 2017). "Next, we tested whether cells that do not endogenously expressed SUN1 and SUN2 protein plays a role on HIV-1 infection." (PMID 34580332, 2021). "While overexpression of SUN1 or SUN2 blocked HIV-1 infection, gene disruption in THP-1 cells had no (SUN1) or modest (SUN2) effects on HIV-1 infectivity, possibly indicating redundancy between the two proteins." (PMID 28747499, 2017). "Although our work shows that overexpression of SUN1 and SUN2 block HIV-1 infection, we did not yet address whether endogenous expression of these proteins are important for HIV-1 infection." (PMID 34580332, 2021). "To identify the step in HIV-1 infection that was impaired in THP-1 cells lacking SUN2 expression, we infected control cells and SUN2 knockout g3c4 cells with DNase-treated VSV-G-pseudotyped NL4.3GFP and isolated total DNA at 6 or 24 h after infection for use in a TaqMan quantiative PCR (qPCR)." (PMID 28747499, 2017).